STAT3 (signal transducer and activator of transcription 3)
Diseases named in the same sentence as STAT3 in open-access papers (continued):
Sharing a sentence is not in itself a finding about the gene and the disease.
prostate carcinoma (continued). "Notable genes in the predicted pathway included ATF3, JUNB, KLF6, NR4A2, ZFP36, DUSP5 and NEDD9, as well as STAT3 and IRF1 as novel upstream regulators, and SELE, CXCL1 and CXCL2 as novel downstream targets of NFκB in prostate cancer." (PMID 27078000, 2016). "Overexpression of STAT3 and its main regulator IL6 is reported in the literature but IL6 inhibitory effect in prostate cancer progression and failure of STAT3-IL6 axis targeting as potential therapeutic target in patients were reported as well." (PMID 28005952, 2016). "Collectively these data support a role of IL-6 in expanding the prostate cancer stem-like phenotype and suggest that ESE3/EHF controls both basal and IL-6 induced STAT3 response." (PMID 27732936, 2016). "In the human prostate cancer cell line DU145, that constitutively express active STAT3, STAT3 inhibition led to the suppression of two anti-apoptotic genes, Bcl-2 and denocarc." (PMID 28008316, 2016). "These miRNAs were found to mediate overexpression of STAT3 and ZEB1, which are key factors in high-grade prostatic intraepithelial neoplasia (HGPIN) and initial stages of prostate cancer." (PMID 28005952, 2016). "Inhibitory effects of silibinin on STAT-1, STAT-3, and STAT-5 phosphorylation were also observed in orthotopic xenograft of PC-3 human prostate carcinoma." (PMID 28030611, 2016). "In prostate cancer, the in vivo effects of CPA-7 on STAT3 and accordingly on immune profile are still need to be clarified." (PMID 27435207, 2016). "Activated-Stat3 is correlated with NPC invasion and metastasis, and RKIP blocks Stat3 activation in prostate cancer cells." (PMID 25915430, 2015). "Recent reports demonstrated synergism between IL-6/STAT3 and PI3K/Akt or Src pathways in promoting prostate cancer aggressiveness and progression." (PMID 26046794, 2015). "Accordingly, oxidative stress triggers STAT3 activation in several cell types, and ROS are involved in EGF-induced STAT3 phosphorylation in prostate cancer, leading to increased pro-tumorigenic action." (PMID 26106584, 2015). "In vitro, IL–20 upregulated N-cadherin, STAT3, vimentin, fibronectin, RANKL, cathepsin G, and cathepsin K, and increased the migration and colony formation of prostate cancer cells via activated p38, ERK1/2, AKT, and NF-κB signals in PC–3 cells." (PMID 26440411, 2015). "Then the STAT3 phosphorylation of ALDHhigh subpopulations in PC3M-1E8 cells and clinical prostate cancer samples were examined." (PMID 25261365, 2014). "In this study, we investigated the role of activated STAT3 signaling on differentiated cancer cell and TIC development in prostate cancer." (PMID 25261365, 2014). "For example, prostate cancer cells express high levels of IL-6, EGF, and EGFR, leading to constitutive activation of JAK2 or Src, which in turn results in STAT3 activation through autocrine and paracrine mechanisms." (PMID 24260381, 2013). "HR prostate cancer (LNCaP-HR and TRAMP-HR) had higher levels of IL-6, more activated STAT3 and AR compared to hormone sensitive prostate cancer cells (LNCaP and TRAMP-C1) shown in our previous and the present study." (PMID 23806095, 2013). "We assessed the role of P-STAT3 in contributing to tumour growth by performing in vitro cell viability growth assays in a panel of ESFT cell lines and in the STAT3-null prostate cancer cell line, PC3." (PMID 22315522, 2012). "Consistent with our results, moderate STAT3 stimulation by adiponectin was noted in MDA-MB-231 cells, while the transcription factor was inhibited in DU145 prostate cancer cells." (PMID 21974986, 2011). "The effect of peptide growth factors on androgen independent proliferation of prostate cancer cells is mainly mediated via the Ras/MAPK, PI3K/AKT and STAT3 signaling cascades." (PMID 20976069, 2010).
prostate carcinoma (continued). "Signal transducer and activator of transcription 3 (STAT3) is activated, as determined by electrophoretic motility shift assays, by EGFR in DU145 and PC3 human prostate carcinoma cells in addition to the motility model NR6 fibroblast cell line." (PMID 16804520, 2006). "In DU145WT human prostate carcinoma cell lines, EGF increased the STAT3-targeted band; herein the antibody to human STAT3 eliminated DNA binding." (PMID 16804520, 2006). "IL-6 signalling is mediated through the Janus kinase (JAK), signal transducer, activator of transcription 3 (STAT3) and mitogen-activated protein kinase (MAPK), which induces AR-mediated gene activation in prostate cancer." (PMID 15150588, 2004). "In contrast, AT1 inhibitors have been shown to inhibit the proliferation of prostate cancer cells stimulated with EGF or angiotensin II, through the suppression of MAPK or STAT3 phosphorylation." (PMID 15813980, 2004). "However, our research also revealed that Osthole can exert anti-prostate cancer effects by binding to PRLR, thereby inhibiting the JAK2/STAT3 pathway." (PMID 40978029, 2025). "In prostate cancer treatment, the PRLR and JAK2/STAT3 signaling pathways are crucial targets." (PMID 40978029, 2025). "In our detailed study of the effects of Osthole on prostate cancer, we found that it could suppress tumor growth and metastasis by targeting the JAK2/STAT3 pathway." (PMID 40978029, 2025). "Subsequently, PPI network analysis was conducted on these targets using the STRING database, which suggested that genes such as AKT1, TNF, IL6, STAT3, and CTNNB1 might be key targets for Osthole in the treatment of prostate cancer." (PMID 40978029, 2025). "Notably, in prostate cancer models, GRK5 knockdown reduced PD-L1 expression by inhibiting STAT3 phosphorylation." (PMID 40722845, 2025). "Cotargeting EGFR and STAT3 with Erlotinib and TTI‐101 impairs both 2D and 3D growth of ETV1‐overexpressing prostate cancer cells by disrupting a self‐sustaining ETV1–EGFR positive feedback loop that promotes EGFR and STAT3 expression and phosphorylation (activation)." (PMID 40808640, 2025). "We here found that LPHNs induced the growth of prostate cancer cells and that the activation of LPHNs was associated with phosphorylation of JAK2/STAT3, but not Akt or ERK1/2, as well as the increased expression of Bcl-2." (PMID 39000396, 2024). "In addition, PMN-MDSCs with high levels of STAT3 activity and ARG1 expression are strongly related to prostate cancer progression, and STAT3 blockade impairs the immunosuppressive effect of PMN-MDSCs on effector T-cell activity." (PMID 38609997, 2024). "ABI1 can also inhibit EMT in prostate cancer by suppressing FYN-signal transducer and activator of transcription 3 (STAT3) activation by non-canonical WNT signaling through a high affinity interaction between the FYN SH2 domain and ABI1 pY421." (PMID 39354505, 2024). "TAMs may also release CCL5, which, through activation of the β-catenin/STAT3 signaling pathway, significantly promoted invasion, metastasis, and EMT in studies using prostate cancer cells." (PMID 38033495, 2023). "Furthermore, it has also been found that the STAT3 signaling contributes to oncolytic NDV-induced ICD in melanoma cells and that targeting STAT3 enhances NDV-induced ICD in prostate cancer cells." (PMID 37009515, 2023). "The results of numerous studies on the therapeutic potential of STAT3 blockers are very promising, but there are currently no such studies focusing on prostate cancer." (PMID 37371647, 2023). "In addition, in prostate cancer, EHF binds to the EBS in the promoter region of IL-6 and represses its transcription, resulting in STAT3 inactivation." (PMID 37958443, 2023). "In prostate cancer DU145 cells, ECA activates protein tyrosine phosphatase 1B (PTP1B) and SH2 domain-containing protein tyrosine phosphatase 2 (SHP2), leading to the inhibition of STAT3 activity and downregulation of the STAT3-responsive gene cyclin D1." (PMID 37047688, 2023).
prostate carcinoma (continued). "Moreover, CGRP activated the signal transducer and activator of transcription 3 (STAT3) and ERK signaling pathways in prostate cancer cells." (PMID 36980580, 2023). "As observed in prostate cancer, CDK5 also phosphorylates STAT3 at S727 in MTC cells." (PMID 37993880, 2023). "Furthermore, in a prostate cancer cell line DU145, Hispolon-induced apoptosis was accompanied by a paralleled decrease in p-STAT3 levels." (PMID 37893115, 2023). "ATL II inhibits cancer cell proliferation and causes apoptosis primarily through regulating the PI3K/Akt, JAK2/STAT3, Ras/ERK, JNK/ERK-Nrf2-ARE, and LncRNA XIST/miR-30a-5p/ROR1 signaling pathways to treat colon, gastric, lung, melanoma, breast, and prostate cancers." (PMID 37241729, 2023). "In agreement with our results, other authors have also shown that, in the absence of pY705, pS727 activates STAT3 signaling and promotes enhancing survival in macrophages, neuronal stem cells, and prostate cancer cells." (PMID 37945711, 2023). "However, no studies have currently reported using a strategy to combat prostate cancer using both blockade of TIGIT and the disruption of the IL6R/STAT-3 axis." (PMID 35465350, 2022). "Moreover, M2 macrophages were found to secrete chemokine CCL5, which promotes prostate cancer cell invasion, migration, and EMT via activating β-catenin/STAT3 pathway, whereas CCL5 knockdown suppresses tumor growth and bone metastases." (PMID 35994202, 2022). "Taken together, this study suggests that enzalutamide may be combined with the STAT3 inhibitor GPB730 in order to enhance the efficacy of anti-androgen treatment, offering an additional therapeutic approach for advanced prostate cancer." (PMID 35917644, 2022). "This study showed an enhanced efficacy of enzalutamide when combined with the STAT3 inhibitor GPB730 in prostate cancer cells which have not previously been exposed to enzalutamide and focuses on the intrinsic resistance to enzalumide treatment." (PMID 35917644, 2022). "This study suggests that enzalutamide may be combined with the STAT3 inhibitor GPB730 in order to enhance the efficacy of enzalutamide, offering a new therapeutic approach in advanced prostate cancer." (PMID 35917644, 2022). "Therefore, this study determines if the combined blockade of IL6R/STAT-3 and TIGIT enhances NK cell cytotoxicity against prostate cancer cells." (PMID 35465350, 2022). "MSC-secreted IL-28 stimulated apoptosis of bone metastatic prostate cancer cells through STAT1 signaling; however, following chronic exposure to IL-28, certain populations of cancer cells became resistant to apoptosis and shifted to STAT3 signaling." (PMID 35994202, 2022). "Wnt, STAT3, Hedgehog (Hh), phosphatase and tensin homolog (PTEN), PI3K/Akt and NF-κB and SPOP are among the signaling networks undergoing abnormal expression in prostate cancer." (PMID 35773731, 2022). "Interestingly, the induction of EMP and invasiveness by IL-6/STAT3 has been shown to be mediated by Fra-1 expression in CRC and by PTTG1 in prostate cancer." (PMID 34361105, 2021). "PDLIM2, Fbw7, and constitutive photomorphogenic 1 (COP1) were identified as E3 ligases for STAT3 in T helper 17 cells, diffuse large B-cell lymphoma (DLBCL) cells, and prostate cancer cells, and several proteins, including TMF/ARA160, are involved in proteasomal STAT3 degradation." (PMID 33859351, 2021). "Rescue experiments confirmed that STAT3 is involved in the regulation of miR-494-3p to inhibit the progression of prostate cancer, and miR-494-3p participates in the modulation of LINC00467 to promote the progression of prostate cancer." (PMID 34094954, 2021). "Interestingly, interleukin-6 (IL-6)-mediated STAT3 activation has been found to up-regulate PTTG1, thus leading to the malignant behaviors of prostate cancer cells." (PMID 34025420, 2021).
prostate carcinoma (continued). "The treatment of prostate cancer cells with stattic, a STAT3 small-molecule inhibitor, reduced the proportion of ALDH+ population in cell lines and clinical prostate cancer specimens and decreased the tumor volume and the percentage of ALDH+ subpopulation in patient-derived tumor xenografts." (PMID 34572930, 2021). "There is one study indicated that B cell-derived lymphotoxin could promote cancer progression in prostate cancer through activate I kappa B kinase (IKK)-α and activator of transcription 3 (STAT3) signaling." (PMID 33613763, 2021). "In addition, 2′-HCA has been found to suppress cancer cell proliferation and tumor growth via the activation of pyruvate kinase M2 and signal transducer and activator of transcription 3 (STAT-3) by regulating ERK1/2 and ROS generation in prostate cancer cells." (PMID 34834209, 2021). "Further research is needed to determine the exact molecular mechanisms of STAMP2 expression by STAT3 and NF-kB signaling crosstalk and how STAMP2 might operate as a survival factor in inflammatory conditions during prostate cancer progression." (PMID 33808059, 2021). "In addition, both extracts reduced the protein expression of phosphorylated STAT3, Snail, and Twist, which are related to the EMT signaling pathway in prostate cancers." (PMID 34298624, 2021). "Moreover, ICD markers induced in prostate cancer cells upon NDV/FMW infection, were enhanced by either treatment with a STAT3 (signal transducer and activator of transcription 3) inhibitor or shRNA‐mediated knockdown of STAT3." (PMID 32100392, 2020). "Moreover, IL-6/STAT3-induced DNMT1 enhances the metastatic potential and reduces radiosensitization in AR-prostate cancer and accumulates myeloid-derived suppressor cells, all of which are responsible for the accelerated tumor growth." (PMID 31952344, 2020). "Altogether, these results indicated that CCL5 could promote prostate cancer invasion and PCSCs self-renewal via activating the CCR5/β-catenin/STAT3 pathway." (PMID 32300100, 2020). "By studying the PLZF/SHP-1/STAT3 signaling pathway involved in CCL3-induced malignancy, we may find a potential therapeutic target for prostate cancer." (PMID 32349303, 2020). "The current data suggest that the high levels of 13-HODE found in GBM cell lines may be influencing GBM growth in a way that is similar to prostate cancer, by inhibiting PPAR gamma activities and increasing STAT3 activation." (PMID 33182324, 2020). "Also, inhibition of IL-6-JAK/STAT3 signalling result in the enhancement of NK cell-mediated cytotoxicity via alteration of PD-L1/NKG2D ligand levels, in castration-resistant prostate cancer cells." (PMID 33569050, 2020). "p‐STAT3, Mcm2, and/or MSR1 were selected out of 10 biomarkers to construct a biomarker index for predicting cancer and high‐grade prostate cancer (HGPCa) in the training cohort based on the stepwise logistic regression analysis; these biomarkers were then validated in the validation cohort." (PMID 32860339, 2020). "In prostate cancer, paracrine IL-6/JAK2/STAT3 stimulates the autocrine IL-6 loop, and IGF-IR activation induced by both IL-6 and IGF enhances EMT through induction of the STAT3/NANOG/Slug axis." (PMID 31952344, 2020). "Consequently, both compounds have increased concentrations in prostate cancer cells and act by inhibition of PI3K/AKT, STAT3 signaling pathways and decreased cancer stem cells activity." (PMID 31936346, 2020). "Furthermore, both STAT3 and STAT5 are reported to play a major role in the progression and pathogenesis of prostate cancer." (PMID 31817042, 2019).
prostate carcinoma (continued). "Thus, dual inhibition of STAT3 and NF-κB by EC-70124 impairs CSC maintenance and tumor development in mice and provides the basis for new therapeutic strategies for treatment of prostate cancer." (PMID 31143708, 2019). "Given its key part in energy metabolism and its link to the protein STAT3, SHMT2 could represent a missing piece to further understand the molecular mechanisms responsible for the transition of prostate cancer towards a more aggressive phenotype." (PMID 31500219, 2019). "Our experiments establish MDA-9 as a critical regulator of stem cell phenotypes in prostate cancer that are responsible for PCSC maintenance and survival through regulation of multiple stem-regulating molecules such as NOTCH1, C-myc, STAT3, NANOG, OCT4 and SOX2." (PMID 31878027, 2019). "This condition could constitute the breeding ground for the evolution of prostate cancer towards a more aggressive form (G9), involving a change in SHMT2 and PKM2 status through the IL-6/JAK2/STAT3 pathway." (PMID 31500219, 2019). "The use of CpG conjugated STAT3-ASO in the treatment of androgen-independent prostate cancer would provide a treatment option for a stage of prostate cancer that currently has no treatment." (PMID 31771198, 2019). "Interestingly, in prostate cancer, the JAK/STAT3 signaling pathway regulates expression of AR and this correlates with decreased survival." (PMID 29928478, 2018). "STAT3 acetylation on Lys685 within the SH2 domain by the histone acetyltransferase (HAT) p300/CBP promotes STAT3 dimerization, DNA binding, and transcriptional activation in human liver and prostate cancer cell lines." (PMID 29728695, 2018). "Prior to determine if this effect is associated with the JAK2/STAT3, protein extracts from prostate cancer cells under the influence of IL-6 with and without the treatment of anti-IL-6R antibody were examined for the phosphorylation of JAK2 and STAT3." (PMID 30134795, 2018). "Importantly, PMN-MDSCs and, to a lesser extent, M-MDSCs isolated from the blood of prostate cancer patients show high surface levels of LIF receptor and respond to LIF stimulation with STAT3 activation and increased T-cell inhibition." (PMID 29921770, 2018). "For example, the antioxidant enzyme Peroxiredoxin II regulates VEGF signaling in liver CSCs by upregulating BMI1 and Sox2 through a VEGFR-2/STAT3 pathway, while VEGF and VEGF receptor neuropilin-2 signaling involved a BMI1-mediated mechanism in aggressive prostate cancer." (PMID 30002682, 2018). "Furthermore, DT can inhibit the migration of prostate cancer cells by interrupting the crosstalk between prostate cancer cells and macrophages via the inhibition of the CCL2/STAT3 axis." (PMID 28157698, 2017). "The objective of this study was to elucidate the mechanism of action of altholactone against prostate cancer DU145 cells and to evaluate whether its effects are mediated by inhibition of NF-κB and STAT3 activity." (PMID 28178219, 2017). "STAT3 activation is observed in 82% of prostate cancer tissues compared to matched adjacent non-cancer tissues, and elevated STAT3 activity was correlated with a malignant phenotype." (PMID 28264478, 2017). "Previous studies have reported that a combination of STAT3, CCL2, and EMT activates prostate cancer progression and may provide a novel therapeutic target for the prevention of prostate cancer metastasis." (PMID 28157698, 2017). "For example, STAT3, AP1, AR, ERG, EGR1 and MYC are important TFs that are responsible for the progression of prostate cancer by affecting a wide variety of pathways involved in cell proliferation and differentiation, apoptosis, tumor suppressing and various cell signaling pathway." (PMID 28005952, 2016). "Remarkably silibinin was able to reverse epithelial-to-mesenchymal transition (EMT) in metastatic prostate cancer cells by down-regulating the two major EMT regulators, ZEB1 and SLUG transcription factors, while its role in inhibiting STAT3 signaling is well documented." (PMID 28042859, 2016).